CD33 (CD33 molecule)
Diseases named in the same sentence as CD33 in open-access papers (continued):
Sharing a sentence is not in itself a finding about the gene and the disease.
acute myeloid leukemia (continued). "In acute myeloid leukemia (AML), the CD33 targeting gemtuzumab ozogamicin has demonstrated modest improvements in survival and is the only ADC currently licensed in the United States for pediatric patients with de novo AML." (PMID 34441852, 2021). "Early clinical trials using anti-CD33 CAR-NK-92 cells showed no major adverse effects in relapsed/refractory acute myeloid leukemia (AML) patients, supporting the notion that CAR-NK cells could be a safe alternative to CAR-T cells in hematological malignancies." (PMID 33304346, 2020). "CD33 is a target in myeloid malignancies, especially acute myeloid leukemia (AML), and CD123 is expressed in different HM, including blastic plasmacytoid dendritic cell neoplasm, hairy cell leukemia, B-ALL, and AML." (PMID 32679920, 2020). "CD33 (M23197) is expressed on the malignant blast cells in most cases of acute myeloid leukemia (AML) but not on normal hematopoietic pluripotent stem cells." (PMID 22830977, 2012). "FCM analysis indicated that the blasts exhibited an immunophenotype consistent with acute myeloid leukemia (AML), showing positivity for CD11c, CD33, CD64, and HLA-DR, while being negative for CD10, CD19, and CD20." (PMID 40755566, 2025). "In previous work, we were able to show the generation of effective CD33-targeting CAR-NK cells for the treatment of acute myeloid leukemia (AML), a disease for which no CAR-T cell therapy is available yet, and which demonstrates dismal overall survival rates especially for elderly patients." (PMID 38253870, 2024). "In a clinical trial of CD33-targeting CAR-NK cell therapy employing NK92 cell lines, patients with acute myeloid leukemia (AML) received up to 5 × 109 CAR-NK92 cells without experiencing any substantial adverse effects or grade 3–4 toxicity in 2018." (PMID 37596653, 2023). "A study reported that Ventx was aberrantly expressed in CD34+ acute myeloid leukemia (AML), and its maximum expression was found in CD33+ myeloid cells but not in normal CD34+/CD38− leukemic cells." (PMID 35269883, 2022). "Infusion of CD33 CAR-NK cells was shown to be safe in this phase I/II study, but no reaction to treatment was seen in patients with acute myeloid leukemia (AML) (NCT02892695 and NCT02944162)." (PMID 34215336, 2021). "Growing evidence of GO efficacy in acute myeloid leukemia (AML), demonstrated by improved outcomes in CD33-positive AML patients across phase I to III clinical trials, led to the Food and Drug Administration (FDA) approval on 1 September 2017 in CD33-positive AML patients aged 2 years and older." (PMID 32781546, 2020). "To determine whether modified mAb-KF retained target specificity, we stained CD33-positive acute myeloid leukemia THP1 cells and CD33-negative acute T cell leukemia Jurkat cells and performed flow cytometry analysis." (PMID 31509944, 2019). "Another nanobody-based tri-specific Tandem CAR (TanCAR) T-cell targeting CD33, CD123, and CLL1 were designed to address antigen-negative escape and intra-tumor heterogeneity in acute myeloid leukemia (AML)." (PMID 40474230, 2025). "Notably, SOS is also an important side effect of gemtuzumab ozogamicin (GO), a CD33-calicheamicin ADC approved for the treatment of acute myeloid leukemia (AML), suggesting that this toxicity is related to the common cytotoxic payload calicheamicin and not specific to either CD22 or CD33 targeting." (PMID 37600823, 2023).
leukemia (156 papers, 2012 to 2026). A malignant (clonal) hematologic disorder, involving hematopoietic stem cells and characterized by the presence of primitive or atypical myeloid or lymphoid cells in the bone marrow and the blood. "CD33 is thought to be associated with immune cell function, susceptibility to Alzheimer’s disease, and rare leukemias." (PMID 40043053, 2025). "Because the myeloid differentiation antigen, CD33, is expressed on at least a subset of AML blasts in almost all patients and possibly on underlying leukemia stem cells in some, immunotherapies targeting CD33 have long been pursued to improve these outcomes." (PMID 38473239, 2024). "Since CD33‐expressing leukemia cells are commonly found in leukemia cells having various gene mutations, this effect was expected." (PMID 36819180, 2023). "Notably, the third generation CD33 CAR-T preferentially killed leukemia cells while sparing CD33-deficient HSPCs." (PMID 36523990, 2022). "Because ABCB1 was highly associated with CD34 and CD33 we postulated that ABCB1 may be a bystander effect inherent to a respective leukemia stem cell (LSC) phenotype." (PMID 31500210, 2019). "All experiments were performed to investigate specifically the efficacy of the employed ULBP2-aCD19-aCD33 against only CD19/CD33-expressing leukemia cells, which are mainly found in resistant antigen loss variants especially described as mixed lineage leukemia (MLL)." (PMID 28943878, 2017). "Furthermore, since NPM1-mutated leukemia cells are associated with increased CD33 expression, CD33 antibodies like gemtuzumab ozogamicin (GO) could be a targeted therapy for those NPM1-mutated patients with high CD33 expression." (PMID 29301553, 2018). "The clinical trial, NCT05008575, currently underway at the Hematology Department of Chongqing Xinqiao Hospital in China targets leukemia cells expressing CD33, employing CAR-NK cells in combination with chemotherapy drugs." (PMID 40726987, 2025). "The CD33/CD3-bispecific T-cell engaging (BiTE®) antibody (AMG 330) exhibited notable efficacy in combating leukemia by specifically targeting CD33+ MDSCs in AML." (PMID 40771826, 2025). "For instance, 90Y-anti-CD20 and 213Bi-anti-CD33 bind to CD20 and CD33, respectively, in lymphomas and leukemias, while 177Lu-trastuzumab binds to the HER2 receptor in breast cancer." (PMID 40725216, 2025). "Since most leukemia cells are associated with the positive expression of specific antigens (such as CD123, CD33, CD96 and CLL-1), targeted immunotherapy, including monoclonal antibodies and bispecific antibodies, is currently in the clinical evaluation stage." (PMID 40129984, 2025). "Decreasing the distance between the antibody-binding epitope within CD33 and the leukemia cell membrane by around 4 nm was sufficient to induce changes in the ADCC activity." (PMID 40564964, 2025). "Preclinical studies based on blood-derived primary NK cells, engineered to express CAR-targeting CD33, have shown consistent antitumor activity in models of CD33-positive leukemias and primary AML blasts." (PMID 40361380, 2025). "For example, erythrocyte-derived EVs effectively delivered anti-miR-214 oligonucleotides to suppress pathological bone resorption, and CD33-targeted EVs carrying miR-125b antisense oligonucleotides enhanced leukemia stem cell clearance." (PMID 40433390, 2025). "Moreover, the depletion of CD33-positive immune cells (such as monocytes) by GO may weaken the patient’s innate immune response, further increasing the risk of infection and indirectly promoting the expansion of leukemia clones." (PMID 41020214, 2025). "CD33’s expression on myeloid progenitor cells and leukemia blasts makes it a prime target for antibody-based therapies, such as antibody–drug conjugates, that seek to selectively eliminate leukemic cells while sparing normal hematopoietic stem cells." (PMID 38254780, 2024).
leukemia (continued). "CD22 and CD33, which are consistently expressed on leukemia and lymphoma cell surfaces, are potent antibody targets in hematological conditions." (PMID 38254780, 2024). "It has been demonstrated that CAR-T cells expressing anti-CD33 and anti-CD3, and anti-CD22 and anti-CD33 CARs, have strong antitumor effects in patients with leukemia and lymphoma." (PMID 38611013, 2024). "Attachment of anti-CD33 antibody and lanthanide oxyfluoride NP or liposome is a proven way for targeting leukemia cells expressing CD33." (PMID 38594732, 2024). "Alongside CD22, we extend our focus to CD33, another prominent Siglec member, which has been scrutinized for its pivotal role in hematological malignancies, especially leukemia." (PMID 38254780, 2024). "The anti-leukemic effects of 17C7 and 20F2 were confirmed by the reduction of human CD45+CD33+ leukemia cells in peripheral blood (PB) and BM of NSG-recipients following treatments." (PMID 38167704, 2024). "In particular, CD33 (Siglec-3) is a definitive marker for myeloid leukemias, and it has emerged as a vital target in leukemia therapeutics, with its expression levels prognosticating the efficacy of gemtuzumab ozogamicin (GO) in AML treatments." (PMID 38254780, 2024). "This targeted approach aims to leverage CD33’s biological function to advance leukemia treatment, highlighting the critical impact of Siglecs in the development of novel cancer therapies." (PMID 38254780, 2024). "CAR-T cells equipped with anti- Siglec-2 (CD22) and anti- Siglec-3 (CD33) receptors exert potent therapeutic effects on leukemia and lymphoma, respectively." (PMID 38254780, 2024). "CC-96191 was broadly active against human leukemia cells in a strictly CD33-dependent manner, with maximal efficacy requiring the co-engagement of CD16a and NKG2D." (PMID 38473239, 2024). "Nevertheless, one promising antigen for CAR-based cell therapy is CD33, which is expressed on leukemic blasts and leukemia-inducing cells in up to 88% of AML patients, and preclinical results have demonstrated anti-AML activity of CD33-specific CAR-T cells." (PMID 39349459, 2024). "In particular, the prevalence of the CD33 antigen together with the fact that high levels of expression in childhood leukemia correlates to adverse disease outcome has focused attention on CD33 as an important immunotherapy target." (PMID 35930221, 2023). "In another approach, the AAV6-CD33 vector carrying an antibody-binding CD33 epitope targeting leukemia cells was utilized for the expression of the inducible caspase 9 (iCasp9) suicide gene in an AML xenotransplantation model in zebrafish." (PMID 36992407, 2023). "In an initial study of Gemtuzumab ozogamicin, the ADC that targets CD33, used a high dose of 9 mg/kg, which was shown to saturate all CD33-expressing myeloid cells and leukemia cells." (PMID 37568702, 2023). "GO binds to CD33‐expressing leukemia cells through its humanized anti‐CD33 monoclonal antibody portion and then kills them with its calicheamicin portion." (PMID 36819180, 2023). "We used CD14 as a marker of myeloid differentiation and CD33 as a marker for immature and aggressive leukemia to characterize our CRISPR/Cas9 MLL-AF4 and MLL-AF9 cells before and following treatment with CAD204520." (PMID 37833915, 2023). "It is conjugated to the cytotoxic agent calicheamicin and released upon binding to CD33, leading to the elimination of CD33-expressing leukemia cells." (PMID 37510328, 2023). "Preclinical research has demonstrated potent leukemia killing of CD33 specific CAR T cells and several clinical trials are ongoing investigating CD33 CAR T cells in both the adult and pediatric populations (NCT03927261, NCT03971799)." (PMID 38137469, 2023). "Among all leukemia subtypes, CD33 exhibited a robust enrichment in AML and CML (chronic myelogenous leukemia), while IL1B correlated best with pediatric ALL and considerably with AML." (PMID 35646901, 2022).
leukemia (continued). "In our study, there was a significant association of the higher expression of leukemia stem cell markers: CD 133 and CD133+/CD33-% at diagnosis, with shorter OS and DFS (p = 0.006 and p ≤ 0.001 and p = 0.029 and p = 0.007)." (PMID 35530356, 2022). "Compared to that of CD33-BiTE, CD33-TriTE induced a stronger proliferative effect on T cells and a more powerful cytotoxicity on leukemia cells with high PD-L1 expression." (PMID 35680594, 2022). "After determining the enhanced accumulation of CD33‐targeting RBCEVs in target cells in vitro, we further verified the specific uptake of RBCEVs by leukaemia cells in vivo." (PMID 35851970, 2022). "The conjugation of RBCEVs with anti‐CD33 antibody led to more than a two‐fold increase in mean fluorescent intensity of CellTrace‐positive leukaemia cells in the bone marrow, liver, and spleen." (PMID 35851970, 2022). "Leukaemia development was monitored by detecting the percentage of human CD45+CD33+cells in mouse peripheral blood every week." (PMID 35851970, 2022). "Taken together, conjugation of RBCEVs with anti‐CD33 antibody significantly promotes the delivery of miR‐125b ASO‐loaded RBCEVs thus enhancing the suppression of leukaemia in patient‐derived AML xenografts." (PMID 35851970, 2022). "On iMSC, the leukemia blasts lose the expression of the myeloid marker CD33+ (myelo-suppressive) while on iANG the blasts retain the expression of CD33 with the emergence of a population of CD15+ cells (myelo-permissive) (Key resources table)." (PMID 35977468, 2022). "The percentage of GFP‐positive leukaemia cells also reduced significantly in the bone marrow, liver, and spleen of the mice treated with CD33‐targeting RBCEVs loaded with FLT3‐ITD ASO as compared to the control groups." (PMID 35851970, 2022). "Flow cytometry analysis revealed that mice treated with miR‐125b ASO‐loaded CD33‐targeting RBCEVs had much lower percentages of human leukaemia cells compared to control mice, indicating lower leukaemic burden and slower leukaemia progression." (PMID 35851970, 2022). "In order to develop an siRNA-based targeted therapy to treat leukemia, we chose the humanized anti-CD33-monoclonal antibody (αCD33-mAB) gemtuzumab as a carrier." (PMID 36457063, 2022). "Siglec-2 (CD22) and Siglec-3 (CD33)-targeting antibody–drug conjugates have been approved by US Food and Drug Administration for the treatment of lymphoma and leukemia." (PMID 34112250, 2021). "Several groups have proposed other resistance mechanisms, such as alternative GO pharmacokinetics and the reduction of CD33 on leukemia cells." (PMID 34203180, 2021). "CD33, a member of the sialic acid-binding Ig-like lectin family, is expressed on subpopulations of leukemia cells, including leukemic stem cells, in almost 90% of AML cases as well as on some normal myeloid precursors." (PMID 33833386, 2021). "Several CAR-NK cells (targeting CD19, CD22, CD7, and CD33) are currently in clinical trials for the treatment of certain types of leukemia or lymphoma (e.g., NCT03056339, NCT04004637)." (PMID 33505304, 2020). "One potential strategy to prevent the risk of bone marrow failure following CAR T cells that target the highly expressed but non-leukemia specific antigens such as CD33 and CD123 is to limit long-term CAR T cell persistence in vivo." (PMID 32435621, 2020). "Since the correlation of CD33 with poorer prognosis in leukemia was established, the running clinical trials implicate the potential of anti-CD33 frontline therapy." (PMID 32575400, 2020). "This agent targets leukemia cells for apoptosis with a cytotoxic payload, calicheamicin, carried by a CD33-specific antibody." (PMID 32117773, 2020). "Since CD33 is abundantly expressed on healthy myeloid cells as well, NKG2DLs, which are leukemia cell-restricted expressed, become promising targets." (PMID 33287858, 2020).
leukemia (continued). "As a result, LSC and AML blasts can be eradicated at largest extent by the cCART and in vitro, the cCART showed specific and potent anti-leukemia efficacy against CLL-1 or CD33-positive on both AML cell lines and primary AML cells." (PMID 31014360, 2019). "CD33-positive leukemia is defined as either presence of CD33 on greater than 20–25% of the leukemic blasts or by CD33 immunofluorescence staining greater than fourfold above background or by 80% CD33-positive cells by flow cytometry." (PMID 30897808, 2019). "CD33 (siglec-3), a well-known target in leukemia therapy, is an inhibitory sialoadhesin expressed in human leukocytes of the myeloid lineage and some lymphoid subsets, including NK cells." (PMID 31143782, 2019). "Equally, potent pre-clinical activity of CD33-specific CAR-T cells displayed in a xenograft leukemia model coincided with pronounced cytopenias emanating from on-target/off-leukemia toxicity against myeloid progenitors." (PMID 31779130, 2019). "Another interesting method recently published is the generation of leukemia specificity by genetic knock-out of CD33 in normal hematopoietic stem and progenitor cells." (PMID 30736352, 2019). "Engraftment and leukemia outgrowth were detected by measuring specific AML markers huCD45+CD13+CD33+ in peripheral blood by flow cytometry." (PMID 30871629, 2019). "To evaluate CAR33 function, we first performed a characterization of CD33 expression on a range of leukemia lines stably transduced with firefly luciferase." (PMID 30524966, 2018). "Adoptive T cell therapy with Chimeric Antigen Receptor (CAR) T cells targeting various leukemia antigens such as CD33 and CD123 are currently under investigation through clinical trials." (PMID 30713535, 2018). "Two of the sctb antibodies targeted a single antigen on leukemia cells (either CD33 or CD123), whereas the third sctb targeted both leukemia antigens." (PMID 28157217, 2017). "The NK-92 cell line engineered to express anti-CD33 or anti-CD7 linked to TCR zeta, CD28 and 4-1BB signaling domains are undergoing clinical trials for CD33+ AML (NCT02944162) or CD7+ relapsed or refractory leukemia and lymphoma (NCT02742727), respectively." (PMID 28955340, 2017). "Previous toxicity studies showed that our TBs also bind high-activated CD33+ NK cells resulted in reduced effector cell stability during the cytotoxic attack on leukemia cells." (PMID 28943878, 2017). "After 2 weeks, human CD33+/CD45+ leukemia cells (0.1–0.5 %) can be detected by FACS in blood samples of the mice." (PMID 26970896, 2016). "Antigens expressed on leukemia blasts or preferentially expressed on leukemia stem cells including CD33, CD45, CD96, CD123, CD135, CLL-1 and T cell immunoglobulin mucin-3 (TIM-3) represent potential targets for antibody-based therapy in AML." (PMID 28018601, 2016). "A single-chain triple-body with specificity for CD19 and CD33 was shown to mediate effective lysis of mixed lineage leukemia cells by dual-targeting and engagement of NK cells (via CD16)." (PMID 27761200, 2016). "Challenging ΔCD19 selected inducible Caspase9-CAR.CD33 T-cells with programmed-death-ligand-1 enriched leukemia blasts resulted in significant killing like observed for the programmed-death-ligand-1 negative leukemic blasts fraction." (PMID 27907031, 2016). "Mice (N = 5) were treated with 1 using dosages of 2.5 and 5 mg/kg/day for 28 days, after which mice were sacrificed and their bone marrow, spleen, and blood were analyzed for human CD33+/CD45+ leukemia cells." (PMID 26970896, 2016). "iC9-CAR.CD33 ATCs would result in the killing of CD33+ leukemia blasts freshly isolated from the peripheral blood or the bone marrow of patients with AML." (PMID 27907031, 2016). "Results of this preclinical model showed similar eradication of leukemia cells as compared to lentiviral transduced CD33 CAR, albeit transient in vitro activity." (PMID 26484338, 2015).